FENDRR (FOXF1 adjacent non-coding developmental regulatory RNA)
Synonyms: lincFOXF1; onco-lncRNA-21; FOXF1-AS1; FOXF1AS1; TCONS_00024240
Gene: Long non-coding RNA gene on chromosome 16 (86,474,525 to 86,509,099, reverse strand). Ensembl gene ENSG00000268388.
Diseases named in the same sentence as FENDRR in open-access papers:
FENDRR is named in the same sentence as 36 diseases in open-access papers, as found by Europe PMC text mining. Sharing a sentence is not in itself a finding about the gene and the disease. The quoted sentences say what the papers report.
lung carcinoma (9 papers, 2018 to 2026). "This is consistent with previous studies, which demonstrated that SMIM25 and FENDRR were significantly downregulated in lung cancer." (PMID 38084139, 2023). "In summary, this study identifies FENDRR and FOXF1 as novel potential tumour suppressor genes in lung cancer and that FENDRR acts by binding to unmethylated FOXF1 promoter." (PMID 32284793, 2020). "FENDRR (FOXF1 adjacent non-coding developmental regulatory RNA) is also one of the most well-known lncRNAs that functions to inhibit tumor including lung cancer." (PMID 31374807, 2019). "Some of these lncRNAs like FENDRR (FOXF1 adjacent non-coding developmental regulatory RNA), UCA1(urothelial cancer associated 1) have been reported to play roles in lung cancer development." (PMID 31374807, 2019). "Collectively, our results identify FENDRR as a context‐dependent regulator that promotes myocardial injury but may exert tumour‐suppressive and immune‐modulatory functions in lung cancer." (PMID 41584723, 2026). "Thus, much more work is still required to determine the detailed mechanisms it functions in lung cancer and the potentiality of FENDRR and FOXF1 as therapeutic targets for lung cancer." (PMID 32284793, 2020). "In this study, we examined the expression levels of FENDRR and FOXF1 in lung cancer patients through qRT-PCR." (PMID 32284793, 2020). "In addition, lncRNAs such as MT1JP, MAGI2-AS3, PLAC2, TINCR, LINC00641, FENDRR (FOXF1 adjacent non-coding developmental regulatory RNA), TRHDE-AS1, and lncRNA-p21 act as tumor suppressors in lung cancer by sponging miRNAs." (PMID 33412752, 2020).
gastric cancer (7 papers, 2014 to 2021). A primary or metastatic malignant neoplasm involving the stomach. "It has been reported that HOTAIR, ANRIL, GAPLINC, GHET1, H19, GAS5, and FENDRR, etc., play roles in the malignant progression of gastric cancer." (PMID 33744848, 2021). "Histone deacetylation was involved in the down-regulation of FENDRR in gastric cancer cells and FENDRR overexpression suppressed invasion and migration by down-regulating FN1 and MMP2/MMP9 expression." (PMID 29069754, 2017). "To explore the molecular mechanism through which FENDRR contributes to invasion and metastasis in gastric cancer, we investigated potential target proteins involved in cell motility and matrix invasion." (PMID 25167886, 2014). "To explore the molecular mechanisms by which FENDRR contributes to the phenotypes of gastric cancer cells, we investigated potential targets involved in tumor invasion and metastasis." (PMID 25167886, 2014). "Histone deacetylation was involved in the downregulation of FENDRR in gastric cancer cells." (PMID 25167886, 2014). "Histone deacetylation contributed to the decreased expression of FENDRR in gastric cancer cells." (PMID 25167886, 2014).
osteosarcoma (4 papers, 2017 to 2025). A usually aggressive malignant bone-forming mesenchymal neoplasm, predominantly affecting adolescents and young adults. "Together, these data suggested that dysregulated lncRNA FENDRR might be associated with the doxorubicin–resistance of osteosarcoma cells in vivo." (PMID 29069754, 2017). "FENDRR was previously reported to regulate the migratory, invasive, and growth capacities of cholangiocarcinoma, osteosarcoma, prostate cancer, and renal carcinoma cells, evidencing its tumor regulator roles." (PMID 40420658, 2025). "Functional analysis revealed that overexpression of FENDRR suppressed doxorubicin resistance, G2/M phase of cell cycle, and promoted cell apoptosis of osteosarcoma cells in vitro and tumor growth in vivo whereas FENDRR knockdown had the opposite effects." (PMID 29069754, 2017).
cervical cancer (3 papers, 2020 to 2024). A primary or metastatic malignant neoplasm involving the cervix. "There is evidence indicating that the lncRNA FENDRR/miR-15b-5p/TUBA1A axis suppresses cervical cancer cell proliferation and invasion 48, and the lncRNA TTN-AS1 suppresses ovarian cancer cell proliferation and invasion by targeting miR-15b-5p and regulating FBXW7 expression." (PMID 38911389, 2024).
colon cancer (3 papers, 2022 to 2025). "KEGG enrichment analysis indicated that the mechanism of FENDRR's involvement in colon cancer development might be associated with the cAMP signaling pathway, and the typical proteins of the cAMP signaling pathway are PKA and CREB." (PMID 40630642, 2025). "Through in vitro experiments, we confirmed that FENDRR overexpression suppresses colon cancer cell proliferation, migratory capacity, and invasive potential." (PMID 40630642, 2025). "Consequently, these results collectively indicate that FENDRR overexpression inhibits colon cancer cell proliferation in vitro." (PMID 40630642, 2025). "Ten RNAs were finally obtained related to colon cancer, which were hsa-miR-2682-5p, hsa-miR-1277-3p, ANGPTL1, SLC22A18AS, FENDRR, PHLPP2, hsa-miR-302a-5p, APCDD1, MEX3A and hsa-miR-509-3-5p." (PMID 36101384, 2022).
colorectal cancer (3 papers, 2017 to 2021). A primary or metastatic malignant neoplasm that affects the colon or rectum. "Then, gain- and loss-of functional experiments revealed that FENDRR negatively regulated the CSC-like traits of colorectal cancer cells." (PMID 34697986, 2021). "Also, in colorectal cancer, FENDRR interacts with miRNA-18a-5p to upregulate the expression of growth inhibitor 4, thus inhibiting the proliferation, migration, and invasion of colorectal cancer cells." (PMID 33178582, 2020). "All in all, although in vivo experiments are needed, this study reveals a novel FENDRR/Sox2 axis necessary for the CSC-like traits and chemoresistance of colorectal cancer cells, which might be a novel biomarker for colorectal cancer and chemotherapeutic efficiency." (PMID 34697986, 2021).
melanoma (3 papers, 2021 to 2025). A malignant, usually aggressive tumor composed of atypical, neoplastic melanocytes. "The SFPQ-enriched lncRNA transcripts most specific to PM were EMX2OS and FENDRR, the latter reported to function as a tumour suppressor in most cancers, including melanoma." (PMID 34218270, 2021). "To test our hypothesis, herein, we characterized the role of FENDRR in melanoma proliferation and nuclear factor kappa β (NF-κB) activation pathways." (PMID 34200642, 2021). "Notably, STAT1 was involved exclusively in Stage 4–specific synergistic relationships within the melanoma network, whereas TNFSF14, STK17B, SAMD3, PLAC8, and LYN were all Stage 1–specific synergistic genes that synergized with FENDRR." (PMID 40728857, 2025).
Sepsis (3 papers, 2020 to 2021). Sepsis is defined as life-threatening organ dysfunction caused by a dysregulated host response to infection. "Significantly, Cheng and his colleagues recently found five lncRNAs (FENDRR, MALAT1, TUG1, CRNDE, and ANCR) were correlated with sepsis-associated mRNA modules perhaps by acting as competing endogenous RNAs (ceRNAs)." (PMID 34483898, 2021). "They identified five sepsis-related lncRNAs, including FENDRR, MALAT1, TUG1, CRNDE, and ANCR, whose functions were highly related with biological processes of sepsis." (PMID 34055659, 2021). "In one previous study, five lncRNAs, including FENDRR, MALAT1, TUG1, CRNDE, and ANCR, were associated with sepsis." (PMID 34483898, 2021). "Five sepsis lncRNAs were ultimately identified, FENDRR, MALAT1, TUG1, CRNDE, and ANCR." (PMID 32471511, 2020). "Five lncRNAs, FENDRR, MALAT1, TUG1, CRNDE, and ANCR, were detected as sepsis regulators based on the interactions among lncRNAs and the identified coexpression modules." (PMID 32471511, 2020). "We identified five sepsis lncRNAs, FENDRR, MALAT1, TUG1, CRNDE, and ANCR, all of which connect five or more sepsis modules, indicating their functions are highly related with biological processes of sepsis." (PMID 32471511, 2020). "Although most of the lncRNAs regulate none or merely a single sepsis module, FENDRR, MALAT1, TUG1, CRNDE, and ANCR connect multiple sepsis modules with the connectivity of 14, 10, 10, 8, and 5, respectively, which are expected to have high potentials to be involved in the sepsis progress." (PMID 32471511, 2020).
breast carcinoma (2 papers, 2019 to 2022). "FENDRR knockdown promoted breast cancer cell proliferation and migration, and suppressed cell apoptosis; in contrast, its overexpression inhibited tumor growth in a xenograft model." (PMID 31106044, 2019).
endometrioid endometrial carcinoma (2 papers, 2021 to 2023). "Some studies have shown that there is an interaction between RNA methylation and lncRNA in tumors, and m6A reader YTHDF2-mediated degradation of lncRNA FENDRR promoted cell proliferation in endometrioid endometrial carcinoma." (PMID 34917609, 2021). "In endometrioid endometrial carcinoma (EEC) cells, YTHDF2 mediates FENDRR degradation promoting tumor cell proliferation." (PMID 37438359, 2023).
lung fibrosis (2 papers, 2021 to 2024). "Therefore, our RNA sequencing data provide new directions to further investigate molecular mechanisms associated with asbestos-induced lung fibrosis and FENDRR functions." (PMID 34445242, 2021). "Depletion of FENDRR increases cellular senescence in human lung fibroblasts, while overexpression of human FENDRR reduces lung fibrosis in the pulmonary fibrosis mouse model." (PMID 39036601, 2024).
alveolar capillary dysplasia (1 paper, 2013). "Several cases of genetic deletions encompassing the neighboring protein coding gene FOXF1, and also FENDRR have been observed in neonates with the lethal lung disorder ‘alveolar capillary dysplasia with misalignment of pulmonary veins’ (ACD/MPV)." (PMID 24381249, 2013).
colon adenocarcinoma (1 paper, 2021). "The role of fetal-lethal non-coding developmental regulatory RNA (FENDRR) has been explored in various cancers; however, its relationship with colon adenocarcinoma/rectum adenocarcinoma (COAD/READ) remains unclear." (PMID 34621665, 2021).
lung adenocarcinoma (1 paper, 2020). A carcinoma that arises from the lung and is characterized by the presence of malignant glandular epithelial cells. "In the present study, we have investigated FENDRR and FOXF1 expression by qRT-PCR and RNA-FISH assays in lung adenocarcinoma patients." (PMID 32284793, 2020).
mesothelioma (1 paper, 2018). A usually malignant and aggressive neoplasm of the mesothelium which is often associated with exposure to asbestos. "Interestingly, FENDRR is among the genes enriched in the epithelioid compared to sarcomatoid mesothelioma cluster based on gene-expression profile." (PMID 29641489, 2018).
myocardial infarction (1 paper, 2026). Gross necrosis of the myocardium, as a result of interruption of the blood supply to the area, as in coronary thrombosis. "Moreover, single‐cell omics analyses revealed spatially resolved expression of FENDRR within stromal and certain immune cell subsets, supporting its role as a molecular bridge in cancer–myocardial infarction comorbidity via the immunity–ferroptosis–exosome axis." (PMID 41584723, 2026).
pancreatitis (1 paper, 2021). Inflammation of the pancreas. "Pancreatitis: In an in vitro rat model of caerulein-induced inflammation of the pancreas, pancreatitis, ANXA2 and FENDRR were found to be increased in pancreatic acinar cells." (PMID 33513839, 2021).
periodontitis (1 paper, 2022). An acute or chronic inflammatory process that affects the tissues that surround and support the teeth. "A number of other long non-coding RNAs, namely Linc0116, Linc00667, CDK6-AS1, FENDRR and DIRC3 have been found to be down-regulated in the blood samples of patients with periodontitis." (PMID 36456933, 2022).
thyroid cancer (1 paper, 2025). "Although our study did not directly investigate these mechanisms, these insights suggest potential pathways through which PCAT-1 and FENDRR could exert their biological effects in thyroid cancer." (PMID 40468332, 2025).
tumor (26 papers, 2014 to 2026). "FENDRR is a recently discovered tumor suppressor lncRNA whose expression is associated with epigenetic regulation of target genes involved in tumor immunity." (PMID 36810034, 2023). "FENDRR’s expression is linked to the epigenetic modulation of genes involved in tumor immunity." (PMID 37760852, 2023). "The tumor suppressor FENDRR (fetal-lethal non-coding developmental regulatory RNA, LncRNA FOXF1-AS1) is another critical lncRNA." (PMID 37760852, 2023). "FENDRR is a tumor suppressor gene in the tumor, which is related to the proliferation, invasion, and metastasis of tumor cells." (PMID 33912133, 2021). "Although the results of most studies suggest that FENDRR functions as tumor suppressor, the roles of FENDRR in cancers is complicated or even contradictory in similar malignant phenotypes." (PMID 33869020, 2021). "Mechanistically, FENDRR can exert tumor-inhibitory functions in colon cancer through repression of Sry‐Related HMG‐BOX‐4 (SOX4) protein." (PMID 32398968, 2020). "We are still far to understand the roles of FOXF1 and FENDRR in the cancer development but there are suggestive functional data that can explain the tumor-suppressor features we have observed." (PMID 32284793, 2020). "Herein, FENDRR downregulation was also observed in ESCC patients’ tumor tissues." (PMID 40420658, 2025). "Previously, FENDRR was revealed to sponge miR-424-5p, displaying its tumor suppressor role in colorectal cancer, and various miRNAs were identified to mediate its function in tumor progression." (PMID 40420658, 2025). "In lung cancer, FENDRR functions as a tumor suppressor by inhibiting cell proliferation, invasion, and metastasis through its interactions with miRNAs and transcription factors involved in tumor progression." (PMID 39201688, 2024). "These discrepancies suggest that the role of FENDRR may be tumor stage- or cell context-dependent, and the function and underlying mechanisms of FENDRR in drug resistance of GC remain to be elucidated." (PMID 33869020, 2021). "Taken together, FENDRR functions as a tumor suppressor in CC." (PMID 32398968, 2020). "However, it is interesting to note that the most PM-specific SFPQ-lncRNA interactors included genes associated with tumour suppressor function, such as EMX2OS and FENDRR, whereas the most A2058-specific SFPQ-lncRNA interactors comprise genes widely reported as oncogenic, such as LINC00511." (PMID 34218270, 2021). "Approximately 84% and 96% of CpG islands were differentially methylated for FENDRR and FOXF1 respectively although mean methylation level difference between tumor and normal was even sensibly higher in the FOXF1 case." (PMID 32284793, 2020). "Mechanistically, FENDRR has been demonstrated to induce the sinking of the DUSP4/CREB/PRKACB signaling pathway and reverse the epithelial–mesenchymal transition (EMT) pathway, thereby inhibiting tumor growth." (PMID 40630642, 2025). "Based on these results, FENDRR and FOXF1 could be postulated to be as potential tumor suppressor genes." (PMID 32284793, 2020). "In the lncRNA group, lncRNA-TOB2P1, LOC100499489, lnc-NMRAL2p, and lnc-NBPF22P were markedly upregulated in tumor tissues, while LINC01093, LOC100130899, LOC200772, and lnc-FENDRR were significantly downregulated in tumor tissues, compared to the adjacent controls." (PMID 31156698, 2019).
cancer (20 papers, 2017 to 2026). A tumor composed of atypical neoplastic, often pleomorphic cells that invade other tissues. "Furthermore, since its essential role in mouse development was identified, FENDRR has also been implicated in multiple human cancers, supporting the utility of IntroVerse in prioritising lncRNAs for investigation." (PMID 36399497, 2023). "Since lncRNAs can play enhancer-like roles to promote the expression of neighboring protein-encoding genes, we assessed whether FENDRR functions by regulating specific FOX family members known to play important roles in cancer drug resistance." (PMID 33869020, 2021). "Lastly, FENDRR was linked to regulation of cancer cell drug resistance." (PMID 33513839, 2021). "Collectively, these findings indicate that FENDRR exerts a pivotal function in the progression of cancer." (PMID 40630642, 2025). "Because HPH has cancer-like phenotypes, such as hyperproliferation and apoptosis resistance, it is possible that FENDRR is involved in HPH pathogenesis." (PMID 36284300, 2022). "FENDRR, a lethal noncoding developmental regulatory RNA in the fetus, has been explored for its role in various cancers." (PMID 35928921, 2022). "LncRNA FOXF1-AS1, also known as FENDRR, with its gene 3099 nt in length, is involved in some types of cancers, including cervical cancer, lung cancer and breast cancer." (PMID 36284300, 2022). "Although the roles of FENDRR in cancer have been elucidated, the specific mechanism of epigenetic modification regulation in FENDRR remains poorly understood." (PMID 36284300, 2022). "We performed next-generation sequencing data analysis and validated expression of three deregulated and cancer associated lincRNAs–MALAT1, H19 and FENDRR–in GIST and adjacent tissues." (PMID 30557328, 2018). "Among the top deregulated lincRNAs, three previously cancer associated lincRNAs—MALAT1, H19 and FENDRR, were significantly upregulated in a discovery cohort." (PMID 30557328, 2018). "Our data add an additional layer of evidence to the link between cancer and cardiovascular disease by highlighting FENDRR as a candidate lncRNA that may connect these two conditions at the molecular level." (PMID 41584723, 2026). "Recent studies on the function of FENDRR have predominantly focused on its role in cancer." (PMID 40630642, 2025). "Nevertheless, although targeting cancer cells and fibroblasts with FENDRR can be beneficial, FENDRR overexpression in epithelia may inhibit epithelial cell proliferation and hinder restoration of organ function." (PMID 33513839, 2021). "This study shows that cancer-imposed changes in DNA hypermethylation may lead to reduced expression of FENDRR and FOXF1 in gastric CAMs." (PMID 30624614, 2019). "Interestingly, some studies have demonstrated that FENDRR in the cytoplasm participates in the progression of cancer through the ceRNA mechanism, suggesting that FENDRR may play a different role according to its subcellular compartment environment." (PMID 36284300, 2022). "Genes such as FENDRR, MALAT1, FUS, and CRNDE were found to be involved in numerous cancer-stage-cell processes." (PMID 40728857, 2025). "Among these DEirlncRNAs included in the model, some have been revealed to be related to the development of cancers, such as LINC00958, FOXF1 adjacent non-coding developmental regulatory RNA (FENDRR), LINC01116, and LINC00941." (PMID 34408216, 2021).
FENDRR also shares sentences with these, for which no sentence is quoted: asthma (1 paper); cardiovascular disease (1); cholangiocarcinoma (1); hypoplastic left heart syndrome (1); lung disorder (1); lymphedema (1); metabolism disorder (1); Myocardial fibrosis (1); ovarian carcinoma (1); prostate carcinoma (1); rectum adenocarcinoma (1); renal carcinoma (1); respiratory failure (1); sarcoma (1); soft tissue sarcoma (1).